DLX4 (distal-less homeobox 4)
Description:
May play a role in determining the production of hemoglobin S. May act as a repressor. During embryonic development, plays a role in palatogenesis.
Synonyms: BP1; DLX7; DLX8; DLX9; OFC15
Tractability: No criterion of Open Targets' tractability assessment is met for any kind of drug.
Gene: Protein-coding gene on chromosome 17 (49,968,588 to 49,974,959, forward strand). Ensembl gene ENSG00000108813.
Subcellular location: Nucleus
Subcellular location (Human Protein Atlas): Nucleoplasm
Gene Ontology:
Molecular function: DNA-binding transcription repressor activity, RNA polymerase II-specific; protein binding; RNA polymerase II cis-regulatory region sequence-specific DNA binding; sequence-specific DNA binding; sequence-specific double-stranded DNA binding; DNA-binding transcription factor activity; DNA-binding transcription factor activity, RNA polymerase II-specific; DNA binding
Biological process: negative regulation of transcription by RNA polymerase II; cell differentiation; embryonic skeletal system development; regulation of DNA-templated transcription; regulation of transcription by RNA polymerase II
Cellular component: nucleoplasm; nucleus; chromatin
Genetic constraint (gnomAD): Loss-of-function variants: 14 observed, 20.72 expected, observed/expected ratio (o/e) 0.68, 90% interval 0.44 to 1.06. The upper end of that interval is the gene's LOEUF score, 1.06, which puts it in group 4 of 6, group 1 being the genes least tolerant of losing a copy. Missense variants: 293 observed, 300.79 expected, observed/expected ratio (o/e) 0.97, 90% interval 0.88 to 1.07. Synonymous variants: 128 observed, 146.48 expected, observed/expected ratio (o/e) 0.87, 90% interval 0.76 to 1.01.
Homologues: Orthologues: chimpanzee DLX4 (99% identical), macaque DLX4 (99% identical), dog DLX4 (83% identical), rabbit DLX4 (82% identical), pig DLX4 (81% identical), rat Dlx4 (77% identical), mouse Dlx4 (75% identical), zebrafish dlx4a (48% identical), zebrafish dlx4b (45% identical), Drosophila melanogaster Dll (40% identical), Caenorhabditis elegans ceh-43 (36% identical), zebrafish bsx (20% identical), and 2 more. Paralogues in human: DLX6 (45% identical), DLX1 (45% identical), DLX5 (36% identical), DLX3 (35% identical), DLX2 (35% identical), NANOG (22% identical), NANOGP8 (22% identical), BSX (20% identical), VENTX (15% identical).
Diseases named in the same sentence as DLX4 in open-access papers:
DLX4 is named in the same sentence as 35 diseases in open-access papers, as found by Europe PMC text mining. Sharing a sentence is not in itself a finding about the gene and the disease. The quoted sentences say what the papers report.
ovarian carcinoma (13 papers, 2010 to 2024). A malignant neoplasm originating from the surface ovarian epithelium. "High expression of DLX4 is associated with reduced survival of ovarian cancer patients and found to stimulate attachment of ovarian tumor cells to peritoneal mesothelial cells in vitro and increase the numbers of peritoneal implants in xenograft models." (PMID 26569327, 2015). "Analysis of datasets of two independent patient cohorts revealed that high DLX4 expression in ovarian cancer is strongly associated with elevated expression of iNOS but not of other nitric oxide synthases." (PMID 25924901, 2015). "High expression of DLX4 is strongly associated with survival of ovarian cancer patients." (PMID 29665298, 2018). "High DLX4 expression in ovarian cancer strongly correlated with elevated levels of iNOS and poor survival." (PMID 34203994, 2021). "An abnormal DLX4 expression level has been reported in inflammatory breast cancer, leukemia, lung cancer, ovarian cancer, and prostate cancer." (PMID 31739630, 2019). "Previous studies have reported homeoprotein DLX4 regulated inducible nitric oxide synthase-mediated angiogenesis in ovarian cancer." (PMID 26593252, 2016). "A recent study has identified that DLX4, frequently overexpressed in breast and ovarian cancers, stimulates repair of DNA DSB induced by TOP2A poisons, thereby decreasing cell sensitivity to the treatment." (PMID 26560244, 2015). "Levels of NOS2 transcripts were also significantly higher in DLX4-High tumors than in DLX4-Low tumors (P = 0.021) in an independent patient cohort (n = 260 cases) from the Japanese Serous Ovarian Cancer Group Study." (PMID 25924901, 2015). "Stronger staining of iNOS was detected in xenografts derived from ES2 ovarian cancer cells that stably expressed DLX4 (+DLX4) than in xenografts derived from vector-control ES2 cells." (PMID 25924901, 2015). "Levels of inducible nitric oxide synthase (iNOS) were evaluated by quantitative RT-PCR, flow cytometry and nitric oxide assays using ovarian cancer cell lines in which DLX4 was overexpressed or knocked down." (PMID 25924901, 2015). "In this study, we identified that DLX4, a homeoprotein that is overexpressed in ovarian cancer, stimulates ovarian tumor angiogenesis by inducing iNOS expression." (PMID 25924901, 2015). "Studies using xenograft models revealed that DLX4 expression in ovarian cancer cells increases tumor microvessel density, implicating a pro-angiogenic function for DLX4." (PMID 25924901, 2015). "Because iNOS is frequently expressed in ovarian cancers and stimulates tumor angiogenesis, we investigated the possibility that DLX4 stimulates iNOS expression." (PMID 25924901, 2015). "Expression of DLX4 in ovarian cancer cells stimulated endothelial cell growth in vitro and increased microvessel density in xenograft models, and these stimulatory effects of DLX4 were abrogated when its induction of iNOS was inhibited." (PMID 25924901, 2015). "Expression of DLX4 and nitric oxide synthases was analyzed in publicly available transcriptional profiles of ovarian cancer clinical specimens." (PMID 25924901, 2015). "Furthermore, expression of DLX4 in ovarian cancer cells potentiated endothelial cell proliferation in vitro and microvessel formation in xenograft tumors." (PMID 34203994, 2021). "To evaluate whether iNOS expression is elevated in ovarian cancers that highly express DLX4, we analyzed published, publicly available transcriptional profiles of clinical specimens from the Australian Ovarian Cancer Group Study." (PMID 25924901, 2015). "In previous studies, we identified that DLX4 increases tumor microvessel density in xenograft models of ovarian cancer, but the underlying mechanism of DLX4 was not clear." (PMID 25924901, 2015). "DLX4, therefore, might contribute to poor outcomes in ovarian cancer, in part, by promoting peritoneal implantation of tumor cells via enhanced CD44 expression and tumor-mesothelial cell interactions in an NF-κB-dependent manner." (PMID 26569327, 2015).
ovarian carcinoma (continued). "We found that high DLX4 expression is associated with increased expression of iNOS but not of nNOS or eNOS in clinical specimens of ovarian cancer, and that DLX4 induces expression of iNOS but not of nNOS or eNOS in ovarian tumor cells." (PMID 25924901, 2015). "Furthermore, iNOS levels were decreased when DLX4 was knocked down in three additional ovarian cancer cell lines (OVCAR8, OVCA429 and TOV112D)." (PMID 25924901, 2015). "We previously identified that DLX4, a homeoprotein that is absent from most normal adult tissues, is expressed in approximately 50% of ovarian cancers and is strongly associated with reduced survival." (PMID 25924901, 2015). "Upregulation of DLX4 increases the metastatic potential of breast cancer cells in vitro and in vivo and of prostate adenocarcinoma, and its expression correlates with advanced disease stage in ovarian cancer." (PMID 23213280, 2012). "In particular, DLX4 overexpression represents a possible prognostic marker in ovarian cancer." (PMID 21108812, 2010). "Several researches identified the prognostic significance of DLX4 in patients with colorectal cancer, breast cancer, non-small cell lung cancer, prostate adenocarcinoma, hepatocellular carcinoma, ovarian cancer, chronic myeloid leukemia, acute myeloid leukemia, and endometrial cancer." (PMID 34124141, 2021). "Similarly, enforced expression of DLX4 in A2780 ovarian cancer cells induced iNOS levels." (PMID 25924901, 2015). "DLX4 induces CD44 by stimulating IL-1β-mediated NF-κB activity, thereby promoting ovarian cancer metastasis." (PMID 38317839, 2024). "DLX4 also induced the expression of CD44 in ovarian cancer cells, and inhibition of CD44 abolished DLX4′s ability of DLX4 to promote tumor-mesothelial cell interactions in these cells." (PMID 34203994, 2021). "Interestingly, interactions between DLX4 and bFGF/FGF2 have been reported in ovarian cancer tissue." (PMID 34834487, 2021).
breast carcinoma (11 papers, 2010 to 2024). "The authors hypothesized that there was an association between amplification of HER2 and DLX4 in breast cancer since both HER2 and DLX4 genes are closely mapped on the long arm of human chromosome 17 but found no obvious gene co-amplification between the two." (PMID 30131852, 2018). "We revealed that DLX4 was highly expressed in multiple types of cancers, such as breast cancer and colon cancer (COAD)." (PMID 37744456, 2023). "Taking these results together, the expression pattern of DLX4 seems to be “contradictory” when contrasted with the methylation condition of DLX4 in human cancers, especially breast cancer." (PMID 35883028, 2022). "In breast cancer, patients whose tumors express high levels of DLX4 respond poorly to topoisomerase II (TOP2)-targeting chemotherapy, which kills tumor cells by inducing DNA double-strand breaks (DSB)." (PMID 34203994, 2021). "In one study, the gene copy number of DLX4 was elevated in about 22% of primary breast cancer and 24% of the cancers with sentinel lymph node (SLN) metastasis." (PMID 34203994, 2021). "DLX4 has been shown to be a potentially useful marker for the aggressive breast cancer subtype, IBC." (PMID 30131852, 2018). "Dlx-2 has been shown to be expressed at higher levels in human breast cancers compared to other Dlx genes, including Dlx-1, Dlx-3, Dlx-4, and Dlx-6, although its precise roles in tumor biology are not clear." (PMID 21917150, 2011). "For instance, Dlx-4 overexpression is observed in ovarian and breast cancers and strongly correlates with high tumor grade, advanced disease stage, and poor prognosis." (PMID 21917150, 2011). "Among the DLX family of homeobox-containing genes, BP1, an isoform of DLX4, was found to correlate with poor prognosis in human breast cancer." (PMID 21108812, 2010). "Moreover, mounting evidence has shown the adverse effect of DLX4/BP1 overexpression on clinical outcome in patients with breast cancer." (PMID 35883028, 2022). "In other work, DLX4 was shown to promote EMT in breast cancer cells through TWIST." (PMID 34203994, 2021). "These included genes/loci previously reported to be methylated in breast cancer (for example SIM1, PAX6, DLX4, RUNX3)." (PMID 20205715, 2010). "However, several studies have also shown the hypermethylation of DLX4 with a role of transcriptional inactivation in stage I NSCLC, uterine cervical LSILs, breast cancer, and CLL." (PMID 35883028, 2022). "Furthermore, knockdown of DLX4 decreased TWIST expression, resulting in reduced migration ability of breast cancer cell lines." (PMID 34203994, 2021). "In mammary tumors, the expression levels of DLX1, DLX3, DLX4 and DLX6 did not significantly differ from those observed in normal tissue (data not shown)." (PMID 21108812, 2010).
lung carcinoma (6 papers, 2012 to 2023). "The methylation of DLX4 was strongly associated with high risk of recurrence and poor prognostic survival in lung cancer patients." (PMID 30704472, 2019). "While DLX4 gene expression has been associated with stimulatory effects on cell mobility, migration, and invasion abilities in breast tumor and preeclampsia placenta, other lung cancer studies have shown the opposite, which makes it difficult to elucidate its role in cleft tissue." (PMID 34834487, 2021). "In this study, we used NSCLC cell lines NCI-H2170 and A549 cells to reveal the role of DLX4 in lung cancer." (PMID 37744456, 2023). "Through TCGA database, we revealed that DLX4 was highly expressed in lung cancer tissues compared to normal tissues, with a high transcript per million." (PMID 37744456, 2023).
clear cell renal cell carcinoma (5 papers, 2021 to 2023). "Moreover, DLX4 played an oncogenic role in clear cell renal cell carcinoma via inducing proliferation and EMT, and was associated with poor prognosis." (PMID 35883028, 2022). "DLX4 could contribute to the progress of clear cell renal cell carcinoma by stimulating EMT." (PMID 37744456, 2023).
cleft lip (4 papers, 2021 to 2022). Congenital defect in the upper lip where the maxillary prominence fails to merge with the merged medial nasal prominences. "A mutation in DLX4 was reported to cause a non-syndromic form of cleft lip and palate." (PMID 34311721, 2021). "In the unilateral cleft lip tissue group the median number of DLX4 positive epitheliocytes was few to moderate (+/++) and it varied from no positive structures to numerous (+++) in the epithelium." (PMID 37733420, 2022). "The median number of DLX4 positive connective tissue cells of the bilateral cleft lip group was few to moderate (+/++) and it ranged from a few (+) positive structures to few to moderate (+/++) immunopositive structures." (PMID 37733420, 2022). "The median number of DLX4 positive structures in the epithelium of the bilateral cleft lip tissue group was few to moderate (+/++) and it ranged from no positive structures to moderate to numerous (++/+++) immunopositive structures." (PMID 37733420, 2022). "There could be a possibility that DLX4 dysfunction might affect tissue growth in postnatal bilateral cleft lip affected tissue by affecting the normal growth and remodeling processes in cleft affected epithelium and connective tissue." (PMID 37733420, 2022). "The exact mechanisms of BARX1 and DLX4 interaction within bilateral cleft lip affected tissue remain relatively unclear but characteristics and correlations between these factors could imply their possible role in bilateral cleft lip pathogenetic mechanisms." (PMID 37733420, 2022). "Median values of semiquantitative evaluation for BARX1, DLX4, FOXE1, HOXB3, and MSX2 immunoreactivity within the control tissue group, unilateral cleft lip tissue group, bilateral cleft lip tissue group, and cleft palate tissue group." (PMID 37733420, 2022). "The aim of this study was to detect and compare the immunohistochemical expression of cleft candidate gene coded proteins (DLX4, MSX2, HOXB3, SHH, PAX7, SOX3, WNT3A, and FOXE1) in the non-syndromic unilateral cleft lip patient tissue and control group tissue." (PMID 33917041, 2021). "Amongst these genes, DLX4, HOXB3, and MSX2 have been recently shown to be involved in the etiology of non-syndromic cleft lip and palate." (PMID 34834487, 2021). "Interestingly, our study revealed that there were statistically significant negative correlations in the bilateral cleft lip tissue which were notified between BARX1 in the connective tissue and MSX2 in the connective tissue and between BARX1 in the connective tissue and DLX4 in the epithelium." (PMID 37733420, 2022).
endometrial cancer (4 papers, 2021 to 2023). Primary or metastatic malignant neoplasm involving the endometrium (mucous membrane that lines the endometrial cavity). "In fact, the role of DLX4 has been widely revealed in several types of cancers, such as renal cancer and endometrial cancer." (PMID 37744456, 2023). "BP1, a splicing isoform of DLX4, is highly expressed in endometrial cancer, which correlates with patient poor prognosis, cancer pathological grade, tumor invasion and metastasis." (PMID 33563334, 2021). "In addition, DLX4 overexpression could promote cell viability and motility and predict poor prognosis in endometrial cancer." (PMID 37744456, 2023). "DLX4 isoform BP1 overexpression promoted cell proliferation, migration in endometrial cancer with clinically prognostic effect." (PMID 35883028, 2022).
orofacial cleft (4 papers, 2020 to 2022). A disorder of facial skeleton that is characterized by cleft lip and/or cleft palate that result in feeding, speech and hearing problems caused by failures during development. "DLX4 has been associated with formation of orofacial clefts in humans where a DLX4 polymorphism (c.546_546delG, predicting p.Gln183Argfs*57) was identified in a mother and her child with a bilateral cleft lip and palate." (PMID 33917041, 2021). "DLX4 has been previously associated with the formation of orofacial clefts." (PMID 37733420, 2022). "Heterozygous variants in DLX4 have been implicated before in Orofacial clefting." (PMID 34311721, 2021).
gastric cancer (3 papers, 2016 to 2025). A primary or metastatic malignant neoplasm involving the stomach. "Our previous analysis identified DLX4 and DLX2 as biomarkers linked to histological grade and prognosis in gastric cancer (GC)." (PMID 41244921, 2025).
hepatocellular carcinoma (3 papers, 2021 to 2022). A malignant tumor that arises from hepatocytes. "In hepatocellular carcinoma, miR-122 was reported to be downregulated; miR-122 was able to bind to the 3′UTR of DLX4 mRNA, resulting in down regulated expression of DLX4 protein." (PMID 34203994, 2021).
nasopharyngeal carcinoma (3 papers, 2022 to 2023). A carcinoma arising from the nasopharyngeal epithelium. "DLX4 dysregulation has been associated with changes in cell proliferation in pathological tissue in the craniofacial region like nasopharyngeal carcinoma." (PMID 37733420, 2022). "Another study reported that DLX4 facilitated the progression of nasopharyngeal carcinoma via upregulation of YB-1, which was similar to our findings." (PMID 37744456, 2023). "Moreover, DLX4 promoted nasopharyngeal carcinoma progression via inducing YB-1 expression." (PMID 35883028, 2022).
ovarian tumor (3 papers, 2015 to 2024). "In this study, we investigated the mechanisms by which DLX4, a homeobox gene that is associated with increased tumor microvessel density, stimulates ovarian tumor angiogenesis." (PMID 25924901, 2015). "Together, our findings indicate that the stimulatory effect of DLX4 on ovarian tumor angiogenesis is substantially mediated through its induction of iNOS." (PMID 25924901, 2015). "DLX4 expression in ovarian tumor cells induced ascites formation in mice and this induction was abrogated when iNOS was inhibited." (PMID 25924901, 2015). "To confirm our in vitro findings, we evaluated whether DLX4 stimulates ovarian tumor angiogenesis via its induction of iNOS by generating mouse i.p. xenograft models from vector-control and +DLX4 ES2 cells and from +DLX4 ES2 cells in which iNOS was knocked down." (PMID 25924901, 2015). "In this study, we identified that DLX4 induces iNOS expression in part by stimulating STAT1 activity and promotes ovarian tumor angiogenesis by inducing iNOS expression." (PMID 25924901, 2015).
preeclampsia (3 papers, 2015 to 2021). Preeclampsia is a hypertensive disorder of pregnancy that is characterized by new-onset hypertension with proteinuria presenting after 20 weeks of gestation, and depending on mild or severe forms may initially present with severe headache, visual disturbances, and hyperreflexia. "Our findings that DLX4 induces iNOS expression raise the intriguing possibility that down-regulation of DLX4 in the placenta might promote endothelial dysfunction in preeclampsia by causing a reduction in iNOS levels." (PMID 25924901, 2015). "What is more, DLX4-mediated EMT in trophoblasts may be a possible pathophysiological mechanism for preeclampsia." (PMID 35095892, 2021).